IL4 (interleukin 4)
Diseases named in the same sentence as IL4 in open-access papers (continued):
Sharing a sentence is not in itself a finding about the gene and the disease.
filariasis (6 papers, 2010 to 2024). "In the context of filariasis, IL-4 and IL-13 have been described as critical cytokines required for the expansion of tissue-resident macrophages that optimally maintain eosinophilic influx and effector responses at the site of infection." (PMID 32571840, 2020). "IL-4 and IL-10 are the key cytokines of effector mechanism in murine filariasis and filarial infections diminish both Th1 and Th2 pathways for survival, therefore, protective immunity required activation of both the arms of immune response." (PMID 27828973, 2016). "A study evaluating PBMC from patients with filariasis, showed that CD4+ T cells are the main source of IL-10 and the majority of these cells co-produced neither IL-4 nor IFN-γ." (PMID 33692784, 2021).
hepatic granuloma (6 papers, 2014 to 2022). A granuloma located in the liver. "Hepatic granuloma formation and fibrosis are upregulated by Th2 and Th17 cells, mainly secreting IL-4 and IL-17A, respectively, and downregulated by Th1 and Treg cells." (PMID 35839247, 2022). "Chronic disease of hepatic granuloma formation and fibrosis are upregulated by Th2 and Th17 cells, mainly secreting IL-4 and IL-17, respectively, and downregulated by Th1 and Treg cells." (PMID 32132991, 2020). "For example, Th2 and Th17 cells were reported to upregulate hepatic granuloma formation by secreting IL-4 and IL-17 respectively, while Th1 and Treg cells were reported to downregulate hepatic granuloma formation." (PMID 24788758, 2014). "The major Th2 cytokine, IL-4, secreted by CD4+ T cells also contributes to the development of hepatic granulomas." (PMID 34977224, 2021).
hepatitis C (6 papers, 2010 to 2025). "The G allele for IL-10 (−1082 A/G), the C allele for IL-4 (+3 C/T) and the C and T alleles for IL-28B (rs12979860 and rs8099917, respectively) are associated with spontaneous viral clearance in hepatitis C infection." (PMID 22986179, 2012). "The allele C of the IL-4 gene is more present in the acute hepatitis C group than chronic group." (PMID 22986179, 2012). "Some studies show that patients with severe hepatitis C had higher levels of IL-4 compared to milder cases and serum IL-4 levels were significantly increased in patients with chronic HCV." (PMID 33435966, 2021). "According to Falasca, IFN-γ and IL-4 are important in the chronic progression of hepatitis C." (PMID 40559733, 2025). "Furthermore, CD163+ monocytes can secrete both pro- and anti-inflammatory cytokines such as TNF-α and IL-4 during Leishmania and hepatitis C infection, which might interfere in instructing T cells and inhibit the killing of intracellular pathogens." (PMID 31779590, 2019). "Another point to note is that the levels of interleukin-4 in HCV-ve are not different from those of HCV+ve, so this cytokine is not an important factor in the development of lichen planus in hepatitis c-positive individuals." (PMID 32134902, 2020).
hookworm infection (6 papers, 2012 to 2025). "Our results show that experimental hookworm infection leads to a strong systemic and mucosal Th2 (IL-4, IL-5, IL-9 and IL-13) and regulatory (IL-10 and TGF-β) response, with some evidence of a Th1 (IFN-γ and IL-2) response." (PMID 22346753, 2012). "Levels of mRNA encoded by the Th2/Th9 genes IL-4, IL-5, IL-13, IL-9 and GATA-3 appeared unaffected by hookworm infection using this technique." (PMID 22346753, 2012). "In contrast, hookworm infection did interfere with antigen-specific IFNγ and IL-17 production by splenic T cells, correlating with strongly enhanced production of IL-4 by splenocytes (but not draining lymph node cells)." (PMID 36753434, 2023).
ileitis (6 papers, 2011 to 2025). "For example, gene networks associated with ileitis were suppressed ~8% (P < 0.05), and included Cd36, Il4, Cd44, Cd4, and Cd40." (PMID 28446880, 2017). "Our results showed that the induction of ileitis was associated with the presence of both Th1- and Th2-type effector responses, since we observed increased secretion of IFNγ, as well as IL-4 and IL-5." (PMID 23977323, 2013). "On the other hand, TH2 cells may directly cause intestinal inflammation, as seen by experiments in which IL-4 expressing CD4+ T cells from mice with ileitis were sufficient to initiate ileitis upon being adoptively transferred in immunocompromised recipients." (PMID 34581755, 2021). "Our results showed that MIF mediated T. gondii-induced ileitis does not affect IL-4 and increase IL-10 and TGF-β expression." (PMID 21977228, 2011). "The expansion of neutrophils in the BALF of SHIP-1−/− mice with ileitis coincided with a significant increase in the key neutrophil regulator G-CSF, while the expansion of eosinophils correlated with significant increases eosinophil regulators in BALF including eotaxin, IL-4 and IL-5." (PMID 39432107, 2024).
iron deficiency (6 papers, 2015 to 2024). "Consistent with the observations herein, iron deficiency has been reported to reduce IL-4 and IL-17A responses." (PMID 39296289, 2024). "In the present study, we demonstrated that iron deficiency led to an enhanced pro-inflammatory response, resulting in a marked increase in serum contents of the inflammatory cytokines, IL-1β, IL-4, IL-6, TGF-β1, and TNF-α and a trend towards increased contents of IL-12 and GM-CSF." (PMID 39296492, 2024). "In the seminal African study, which examined the immune status of children with or without iron deficiency, a marked elevation of the Th2 mediator interleukin 4 was also seen in children with iron deficiency, but not in iron-repleted children." (PMID 35769558, 2022).
Kawasaki disease (6 papers, 2014 to 2023). A rare inflammatory disease characterized by an acute febrile, systemic, self-limiting, medium-vessel vasculitis primarily affecting children. "In Kawasaki disease, there is evidence of imbalanced Th1/Th2 cell responses, and the plasma level and mRNA expression levels of Th1 cytokines (IFN-γ, IL-2) and Th2 cytokines (IL-4 and IL-10) are markedly elevated during the acute stage of Kawasaki disease." (PMID 37841239, 2023). "In our previous research we have found that patients with Kawasaki disease had higher levels both M1 related cytokine TNF-α, and the M2 related cytokines IL-6, IL-4 and IL-13 in the acute phase of Kawasaki disease, which decreased after IVIG therapy." (PMID 35154107, 2022). "RBC, HB, CK, CK-MB, ALB, A/G, LC3II, ATG16L1 were positively correlated with BECN1; the incidence of IVIG-resistant Kawasaki disease, length of stay, lymph node enlargement, perianal desquamation, CAL, IL-4, IL-6, CRP, PCT, SF, CD3 + CD4 + T, and r-GT were negatively correlated with BECN1." (PMID 38114939, 2023). "In addition, urinary IL-4 from Kawasaki disease patients with or without coronary artery lesion (CAL) were compared by Mann–Whitney U test and showed IL-4 was significantly higher in the CAL group." (PMID 34679555, 2021).
kidney damage (6 papers, 2012 to 2025). "Study of −592C/A polymorphism of IL-10 revealed positive significant association between CC carriers and nephropathy (P = 0.001) and study of −590C/T polymorphism of IL-4 revealed positive significant association between CT carriers and nephropathy (P < 0.001)." (PMID 26587547, 2015). "Furthermore, there was also an increase in key anti-inflammatory cytokine levels, such as IL-10 and IL-4 after AT, which is also essential to reduce kidney damage." (PMID 34621463, 2021). "In IL-4/STAT6 KO mice, kidney damage is more severe in IRI-AKI models, underscoring IL-4’s protective role." (PMID 40521043, 2025). "Modulation of the IL4 pathway during ESRD may be due to an intracellular regulation involving different pathways but also could be possible that polymorphisms within the IL4R gene could alter the signalling pathway of IL-4, leading to a progression or prevention of kidney damage." (PMID 22817530, 2012). "While serum levels of IFN-γ, IL-2, IL-4, and IL-12 did not display a difference between experimental groups (data not shown), expression of IL-5, IL-6, TNF-α, IL-10, CXCL1, and IL-1β was elevated in the NZM2410/J mice displaying signs of severe kidney damage." (PMID 28491039, 2017).
lymph node metastasis (6 papers, 2007 to 2026). "Supporting notion on protective function, lower IL-4 immunoreactivity has been demonstrated in colorectal tumors from CRC patients with lymph node metastases or gastric tumors from patients with stage III/IV cancers." (PMID 32512917, 2020). "Fold-change in IL4 transcript number was significantly lower in ESCC patients with lymph node metastasis." (PMID 32512917, 2020). "The results indicated a significant correlation between IL-2 (P ═ 0.025), IL-4 (P ═ 0.005), IL-8 (P ═ 0.009), IL-10 (P ═ 0.017), IL-12p70 (P ═ 0.002), IL-17 (P < 0.001), TNF-α (P < 0.001), and IFN-γ (P ═ 0.026) and lymph node metastasis." (PMID 38920620, 2024). "In GC, IL4 transcript number in tumor tissue tended to positively correlate with TNM stage (ρ = 0.48, p = 0.082) and to be higher in tumors from patients with lymph node metastasis (4.5 vs. 1.6, p = 0.091)." (PMID 32512917, 2020). "The results showed that there is a statistically significant correlation between the expression level of IL-2 (P ═ 0.010), IL-4 (P ═ 0.028), IL-10 (P ═ 0.011), IL-12p70 (P ═ 0.034), IL-17 (P ═ 0.024), TNF-α (P ═ 0.003), and IFN-γ (P ═ 0.007) and lymph node metastasis." (PMID 38920620, 2024). "The expression levels of IL-2 (P ═ 0.010), IL-4 (P ═ 0.028), IL-10 (P ═ 0.011), IL-12p70 (P ═ 0.034), IL-17 (P ═ 0.024), tumor necrosis factor (TNF)-α (P ═ 0.003), and interferon (IFN)-γ (P ═ 0.007) were related to lymph node metastasis." (PMID 38920620, 2024).
neuropathy (6 papers, 2010 to 2025). A disorder affecting the nervous system that manifests with pain, tingling, numbness, and/or muscle weakness. "Decreased expression in immunosuppressive cytokines like interleukin-4 (IL-4) or interleukin-10 (IL-10) is also significant between pain and painless neuropathy." (PMID 38026483, 2023). "For example, the mice with oxaliplatin-induced neuropathy have increased interleukin-4-positive lymphocytes in the spleen and decreased regulatory T cells in the lymph node, whereas no such phenomena are detectable in the mice with paclitaxel-induced neuropathy." (PMID 31666085, 2019). "However, nerve cells can mitigate nerve damage and neuropathy by producing anti-inflammatory cytokines such as transforming growth factor-β (TGF-β), IL-4, IL-10, and IL-13." (PMID 40718454, 2025). "Patients with painful neuropathy had a two-fold increase in IL-2 and TNF, while patients with nonpainful neuropathy had significantly higher mRNA levels of IL-4 and IL-10." (PMID 21994811, 2010). "A recent study investigated mRNA levels of proinflammatory cytokines interleukin-2 (IL-2) and tumor necrosis factor-alpha (TNF) as well as anti-inflammatory cytokines IL-4 and IL-10 among patients with painful neuropathy, nonpainful neuropathy and control participants." (PMID 21994811, 2010).
non-Hodgkin lymphoma (6 papers, 2014 to 2025). Distinct from Hodgkin lymphoma both morphologically and biologically, non-Hodgkin lymphoma (NHL) is characterized by the absence of Reed-Sternberg cells, can occur at any age, and usually presents as a localized or generalized lymphadenopathy associated with fever and weight loss. "While the IL-4-stimulated isotype effector function in the mouse and human cannot be directly correlated, elevated levels of IgE have shown to be a prognostic marker of poor outcome for KSHV non-Hodgkin lymphomas and associated with the extent of KS lesion development." (PMID 30619193, 2018). "CD40L and IL-4 increased HLA-E expression on the surface of primary CLL cells and non-Hodgkin’s lymphoma (NHL) cell lines, and this decreased NK cell-mediated ADCC via ligation of the inhibitory receptor NKG2A." (PMID 40977848, 2025).
pancreatitis (6 papers, 2006 to 2023). Inflammation of the pancreas. "Our present study showed that ghrelin enhances the pancreatitis-evoked increase in plasma level of IL-4." (PMID 28665321, 2017). "The aim of this study wasto investigate the association between early changes (within 24 hours) in theserum IL-2, IL-4, TNFα, and IL-6 concentrations and occurence ofsubsequent pancreatitis complication after ERCP." (PMID 18670651, 2008). "Surprisingly, basal IL-6 levels inthe patients with post-ERCP pancreatitis positively correlated with basal CRPlevels, but negatively correlated with basal IL-4 levels." (PMID 18670651, 2008). "CRP was negatively correlated with IL-4 levels at 24 hours afterERCP in the patients with post-ERCP pancreatitis that supports the dominance ofinflammatory activity at this time after ERCP." (PMID 18670651, 2008). "Furthermore, PARP inhibitors have demonstrated effects on reducing pro-inflammatory mediators in the plasma such as TNF-α, IL-1β, IL-2, IL-4, IL-6, IL-12, IP-10, and KC on in vitro models of pancreatitis as well as in vivo models of wound healing injuries." (PMID 33663560, 2021). "In the antisense treated rats with pancreatitis there was 3.5-fold greater serum amylase, increased tissue edema and histological inflammatory scores, and elevated levels of IL-1α, IL-1β, and IL-4 mRNAs in peripheral blood monocytes compared to rats treated with a sense oligonucleotide." (PMID 16700916, 2006). "At this stage of cancer development IL-4 is not detected, which is a major difference to pancreatitis, in which a M1/M2 switch is induced mostly by IL-4 secreted from pancreatic stellate cells." (PMID 37638028, 2023). "We found that the serumlevels of IL-4 at 24 hours after ERCP were lower in the patients with post-ERCPpancreatitis and control group patients than in those of the patients withoutpost-ERCP pancreatitis." (PMID 18670651, 2008). "In the patients without post-ERCP pancreatitis, thelevels of IL-4, TNFα, and IL-6 at 24 hours after ERCP were also higherthan those of the basal levels." (PMID 18670651, 2008). "In the patients without post-ERCP pancreatitis, a positive correlationwas found between IL-4 and TNFα levels at 24 hours after ERCP (r = 0.397; P = .018),but there was a negative correlation between IL-4 and IL-6 levels at 12 hoursafter ERCP (r = 0.392; P = .018)." (PMID 18670651, 2008). "The levels of IL-4 at 24 hours after ERCP were significantly lower in the patients with post-ERCP pancreatitis than in those without pancreatitis, while TNFα levels at 12 hours after ERCP were higher in the complicated group than those of the uncomplicated group." (PMID 18670651, 2008). "The ratios of TNFα/IL-4 at 12 and 24 hours after ERCP were found significantly higher in the patients with post-ERCP pancreatitis than in those without pancreatitis." (PMID 18670651, 2008). "Thelevels of IL-4 at 24 hours after ERCP in the patients with post-ERCPpancreatitis and the control group patients were significantly lower than inthose without ERCP-induced pancreatitis." (PMID 18670651, 2008).
rheumatic diseases (6 papers, 2010 to 2024). "Interleukin-4 (IL-4) has recently been shown to play a function in the pathogenesis of rheumatism." (PMID 37759705, 2023). "The effect of rheumatism in the JWFSN-middle and JWFSN-high dose groups is particularly obvious, suggesting that the therapeutic effect of JWFSN on CIA rats may be through direct or indirect reduction of TNF-α, IFN-γ, and IL-1β expression and improve IL-4 and IL-10." (PMID 31929822, 2019).
skin tumor (6 papers, 2016 to 2025). "Interestingly, in the skin γδ T cells have been shown to be essential in producing IL-4 production and influencing B cell class switching to IgE, which is essential in skin tumour surveillance." (PMID 36599893, 2023). "Our study showed that CXCL17 expression was decreased in the skin tumor of CCL17 TG mice, while IL-4 expression was increased." (PMID 33670758, 2021). "In lesions of various skin cancers, CD163+ macrophages are a main component of TILs that can produce various chemokines by stimulating cancer-specific stromal factors such as POSTN, IL-4, and RANKL." (PMID 29643991, 2018).
synovitis (6 papers, 2005 to 2024). Inflammation of a synovial membrane. "IL-4, IL-18, IL-7, and IL-12 represent effector cell function and are involved in the perpetuation of synovitis and chronic synovitis." (PMID 38675400, 2024). "T cells take part in the inflammatory process of RA mainly by secreting cytokines, such as IFN-γ and IL-4, which is an important link in the development of synovitis." (PMID 39290616, 2021). "Results showed that combined MSC and IL-4 treatment alleviated signs of synovitis in CIA mice, reverting to the values of healthy controls." (PMID 31382595, 2019). "In the unstable stifle at diagnosis, histologic synovitis was inversely correlated with expression of IL-4 in synovium (SR = −0.77, p = 0.001)." (PMID 21998650, 2011). "Early RA synovial fluid was characterized by significantly elevated levels of T cell related cytokines (IL-2, IL-4, IL-13 and IL-17) and stromal cell and macrophage related cytokines (EGF, bFGF, IL-1 and IL-15) when compared with synovial fluid from patients with other early synovitis." (PMID 15987480, 2005). "The levels of plasma epidermal growth factor (EGF), colony stimulating factor 2 (CSF2), interleukin 4/13 (IL4/13), fibroblast growth factor 2 (FGF2) and MIP-1 α were significantly lower in patients with a joint bleeding compared to patients without a bleeding or synovitis." (PMID 33023246, 2020).
toxoplasmosis (6 papers, 2008 to 2025). A parasitic disease contracted by the ingestion or fetal transmission of toxoplasma gondii. "Thus, the notably increased levels of IL-10 and IL-4 in this work could be beneficial to prevent excessive Th1-type responses from causing pathological damage to mice and in combating toxoplasmosis." (PMID 40551280, 2025). "During the acute phase of toxoplasmosis, the concomitant IL-10 and IL-4 responses dampen systemic type-1 cytokine production and prevent lethal immunopathology." (PMID 38029261, 2023). "Apart from IL-7 and IL-15, potential role of other γc family members like IL-4 and IL-21 that have been implicated in CD8 memory generation in other infectious disease models, need to be considered in future investigations of memory CD8+ T cell development during toxoplasmosis." (PMID 20520779, 2010). "The presence of the same pathology in mice without NRAMP, IL-4, IL-6, or IL-13, each important in immunity to toxoplasmosis, indicates that none of these genes or cytokines are necessary or sufficient to cause this histopathology." (PMID 18947414, 2008).
acute GVHD (5 papers, 2002 to 2025). "This suggests that IL-4 should theoretically suppress acute GVHD while promoting the development of chronic GVHD." (PMID 40943537, 2025). "Additionally, exogenous administration of IL-4 demonstrates alleviating effects on acute GVHD.The Charles S. Via team conducted a systematic investigation into the mechanism of IL-4 action within a non-irradiated parent-to-F1 GVHD model, which simulates kidney transplant rejection." (PMID 40943537, 2025). "Injection of GMSCs into mice with acute GVHD significantly reduced the percentages of cells secreting pro-inflammatory cytokines such as IFN-γ, IL-17, IL-4, and TNF-α." (PMID 30622237, 2019). "To determine whether GMSCs could suppress acute GVHD through controlling cytokine production by staining with IFN-γ, IL-17, IL-4, TNF-α, IL-2, and IL-10, we detected the production of cytokines after injecting 15 days." (PMID 30622237, 2019).